CD44 (CD44 molecule (IN blood group))
Diseases named in the same sentence as CD44 in open-access papers (continued):
Sharing a sentence is not in itself a finding about the gene and the disease.
tumor (continued). "β-Ga2O3:Cr3+ NPs modified with hyaluronic acid (HA) could effectively absorb antineoplastic drugs, and they were shown to bind with CD44, which is highly expressed in tumor cells and is primarily distributed at the tumor site." (PMID 29441243, 2018). "In addition, the researchers succeeded in isolating and identifying cancer stem cells from human glioma tissue by using surface molecules (CD133, CD44), side population sorting, and tumor globulogenesis analysis." (PMID 30344611, 2018). "Tumor-initiating cells are enriched in the CD44+/CD24–/low cell population." (PMID 30367042, 2018). "However, tumors originated from CD44 high/EMT/chemoresistant cells showed expression of CD44v suggesting a dynamic switch of CD44 isoforms during tumor formation." (PMID 29747682, 2018). "Moreover, CD62 is also expressed on platelets and its binding to CD44 creates a coat that protects tumor cells from cytotoxic effector cells in in vivo models." (PMID 30200242, 2018). "Notably, the KEGG pathway set “proteoglycans in cancer” contained tumor stemness processes indicated by CD44." (PMID 30275459, 2018). "The ability of CD44 expression in biopsies and transurethral resections to predict tumor aggressiveness in prostatectomies had been evaluated, as had the association of biopsies and transurethral resections with anatomopathological factors and tumor progression." (PMID 29682524, 2018). "This may be a reason we could not obtain sphere-forming cells by the primary cell culture of the tumor tissues expressing a low P/C ratio for CD44." (PMID 30210550, 2018). "We first determined whether PLXDC1 and CD44 expression in the tumor neovasculature of cancer patients in an effective target." (PMID 29890852, 2018). "The same treatment group had a larger proportion of CD4+ T and CD8+ memory/effector T cells (CD3+CD4+CD44+ and CD3+CD8+CD44+, respectively) among tumor-infiltrating leukocytes, suggesting that the anti–MMP-9/anti-PDL1 combination promotes a functional T cell–mediated antitumor response." (PMID 30500835, 2018). "In a recent study, flow cytometry showed that the liver metastatic CRC patients with high expression of CD133+ CD54+, CD133− CD54+, and CD133+ CD44+ CD54+ cellular subpopulations of circulating tumor cells had a worse survival than those patients with low expression." (PMID 30282914, 2018). "The group also reported divergent effects of CD44, depending upon the specific tumor environment." (PMID 29236307, 2018). "CD44-deficient CAFs do not sustain CSC suggesting that CD44 expressed on CAFs serves as a functional molecule that contributes to the maintenance of cancer stem cell populations in the tumor microenvironment." (PMID 29747682, 2018). "EpCAM-/CD44+ cells may represent tumor cells that have undergone EMT and/or are circulating cancer stem cells (cCSCs)." (PMID 29868579, 2018). "CD44, one of these markers, is a multifunctional class I transmembrane glycoprotein that is highly expressed in most cancer types, where it contributes to tumor progression." (PMID 30100995, 2018). "Furthermore, HA was also identified as a novel marker of VMs showing an important function for CD44 in the formation of vascular-like tumor cell networks." (PMID 29378465, 2018). "For example, prominent focal amplifications of chromosome 1 could be detected in the primary tumor, the unsorted pleural sample and in the CD44+ cell fraction." (PMID 28423035, 2017). "In addition, a direct suppression of tumor angiogenesis through inhibition of CD44 expression was demonstrated in a murine model of bladder cancer." (PMID 28474282, 2017). "Dr. Wicha's group has elegantly summarized and proposed to target CSC via CSC surface markers, such as ALDH (aldehyde dehydrogenase), CD44, CD133 and HER2, or the CSC niche, such as tumor associated macrophages and myeloid-derived suppressor cells, using immunologic approaches." (PMID 27903969, 2017).
tumor (continued). "Thus, the CD44+/CD24− state not only can serve as a substrate for but also can spur tumor evolution by promoting continued acquisition of genetic diversity." (PMID 28092266, 2017). "Cells producing low levels of CD44 have lower ability to form tumor sphere in vitro." (PMID 28326306, 2017). "Therefore, CD44v6 has attracted more interest than CD44 in terms of tumor markers, diagnosis, and treatment." (PMID 28030817, 2017). "Immunofluorescence staining shows that the tumor-sphere-derived BCSCs could stably express cancer stem cell markers CD44 and CD133." (PMID 29176652, 2017). "In addition, the expression of the stem cell marker Cd44 was significantly increased in the tumor cells of invasive areas." (PMID 28628120, 2017). "In our study, we demonstrated that ICG-001 could inhibit the growth of tumor spheres and reduce the expression of CD44 as well as other stem cell markers such as OCT-4, Sox2, Nanog, Survivin." (PMID 28893318, 2017). "Moreover, we found the expression of BMI1, ALDH1 and CD44 was also upregulated in the Tgfbr1/Pten 2cKO SCCHN mice tumor." (PMID 28865486, 2017). "The difference between tumor stem cells and CD44+CD117+ stem T cells is worthy of exploration." (PMID 28279199, 2017). "In contrast to in vitro data, we observed a significant inhibition of tumor growth in vivo in MDA-MB-231 cells (95-98% CD44+/CD24−/low; relatively high level of OCT3/4) in contrast to MCF-7 or T-47D cells (1-10% CD44+/CD24−/low; relatively low level of OCT3/4) upon TRIM28 knockdown." (PMID 27845900, 2017). "Also, Activated Gli1 was found in 85% of CD44+ tumor cells suggesting that Gli1 was a potential molecular target." (PMID 29029546, 2017). "Antibody against CD44 eliminated bulk tumor cells as well as TICs from the tumors." (PMID 28245823, 2017). "Prostate CSCs could be found by using the adhesion molecule CD44 as a marker, as CD44 was shown to increase potential for tumor progression." (PMID 28783103, 2017). "In addition, CD44 has been shown to directly interact with MMP-14 (MT1-MMP) to promote tumor cell invasion." (PMID 29348826, 2017). "Recently, it is found that CD44 expression is high in fibroblasts of tumour microenvironment." (PMID 28523716, 2017). "Indeed, the percentage of CD44+CD117+ cells was significantly lower in tumor harvested from combined-treated mice (carboplatin+chloroquine) compared with untreated or single-treated mice." (PMID 28726781, 2017). "Somatic variants present in both the bulk tumor and tumor EPCAM+CD44+CD49f+ subpopulations were categorized as shared (37/51, 72.5%), enriched in the bulk tumor (5/51, 9.8%), or enriched in the tumor EPCAM+CD44+CD49f+ cells (9/51, 17.6%)." (PMID 28487492, 2017). "First we examined CD44 expression in a number of GBM tumor cells and stem cells." (PMID 28279210, 2017). "The fact that RAP is mainly present in the cytosolic compartment and only few molecules appear associated to LRP1 at the outer cell surface, it is reasonable to assume that A2M* plays a dominant role in regulation of CD44 expression in tumour cells compared to RAP." (PMID 29281661, 2017). "To confirm whether the protein level of CD44v8-10 is also elevated in tumour tissues, we performed immunohistochemistry using CD44 variable exon 9 specific antibody (RV3) on patients with high CD44v8-10 expression in tissue samples." (PMID 28694503, 2017). "Thus, by modulating the CD44 turnover, the function of CD44 in cell adhesion and migration is exploited to mediate tumor cell migration." (PMID 29062810, 2017). "Furthermore, the level of SOX9 as well as CSC marker CD44 and mesenchymal marker vimentin in tumor xenografts was dramatically diminished by the treatment." (PMID 29237490, 2017).
tumor (continued). "The origins of the cancer-initiating cells in STICs remain unclear, but tumor-initiating cells that are CD44+ have been isolated from mammary epithelial cells and colorectal cancer cells and characterized as stem cells." (PMID 29100356, 2017). "Location of tumor, tumor size, histologic type, lymphatic invasion, vascular invasion, pathological T stage, pathological TNM stage, residual tumor, and 5-year survival were significantly associated with risk of positive for CD44 staining." (PMID 29445738, 2017). "CD44, a transmembrane molecule with several isoforms, is overexpressed in many tumors, including GBM and has been implicated in malignant processes including cell motility, tumor growth, and angiogenesis." (PMID 29228611, 2017). "Furthermore, human tumor tissues of several entities, including gliomas, breast, lung, colon, and ovarian carcinomas, have shown an increased cleavage of CD44 within the extracellular domain." (PMID 29062810, 2017). "As in the case of other biomarkers, the utility of CD44 as a diagnostic and/or prognostic marker was originally suggested because of its altered overexpression in human tumor tissues as compared with the nontumor or corresponding normal tissues." (PMID 28403901, 2017). "Further, the platform presents the ability for users to assess different areas of the FNAB tumor sample and with coordinating protein markers such as EpCAM and CD44 to know which cells are undergoing cell death or continued viability and evasion of drug response." (PMID 28085924, 2017). "Therefore, the ability of CD44 to localize proteolytically active MMP-9 to the tumor cell surface is important for tumor invasion." (PMID 28326306, 2017). "GBM tumor cells expressing CD44 could attract stem cells, however inhibition of CD44 expression abrogated tumor cell mediated chemotactic activity towards the stem cells." (PMID 28279210, 2017). "In many studies, it has been suggested that exposure to IL-21 alone results in lymphocytes that remain in or differentiate into a minimally differentiated phenotype (CD62L+CD44–), and that these lymphocytes have greater anti-tumor capacity relative to cells expanded in other γ chain cytokines." (PMID 28146052, 2017). "Immunohistochemistry studies showed positive staining on the cell membrane and cytoplasm in paraffin sections incubated with Biotin-RP-1 peptide or anti-CD44 antibody, indicating that RP-1 might bind to tumor cells through CD44." (PMID 28415792, 2017). "A similar trend of tumour-inhibitory effect of miR-141 on CD44+ VCaP cells was also observed." (PMID 28112170, 2017). "By flow cytometry, both normal and tumor CR cells expressed basal, luminal, and stem cell markers, with the majority of the normal and tumor CR cells expressing prostate basal cell markers, CD44 and Trop2, as well as luminal marker, CD13, suggesting a transit-amplifying phenotype." (PMID 28009986, 2017). "Furthermore the combined expression of CD117 and CD44 defined a subpopulation of OC cells endowed with tumor-initiating capacity and chemoresistance." (PMID 28320418, 2017). "Anti-CD44 antibody positive staining could be found in tumor cells and some lymphocytes, whereas RP-1 was positive only in tumor cells." (PMID 28415792, 2017). "Osteopontin (OPN), a secreted tumor-associated, noncollagenous phosphoprotein is an extracellular matrix component and a cytokine through binding to its receptors integrin and CD44." (PMID 28403901, 2017). "Accumulating evidence shows that the genes E-cadherin and CD44 are involved in tumor metastasis." (PMID 28808653, 2017). "Here we found that A2M* increases the expression of CD29 and CD44 in different tumour cell lines." (PMID 29281661, 2017). "Gene expression in tumor EPCAM+CD44+CD49f+ cells further segregated intratumoral from lymph node EPCAM+CD44+CD49f+ cells with 381 genes differentially expressed, including upregulation of genes involved in immune responses and cell adhesion (Gene Ontology) in lymph node EPCAM+CD44+CD49f+ cells." (PMID 28487492, 2017).
tumor (continued). "CD44, is one kind of transmembrane glycoprotein, which was found to be involved in various cellular functions containing hematopoiesis, cell migration and tumor metastasis." (PMID 27791988, 2017). "CD44 in cancer cells interacts with hyaluronan-rich microenvironments modifying cell signaling pathways that trigger the ability of malignant cells to migrate, to invade basement membranes and to lodge at distant sites of the tumor." (PMID 28403901, 2017). "The CD44+CD24+ESA+ cells as a reflection of stemness is generally confirmed with the fact that cells enriched for CD44+CD24+ESA+ were far more tumorigenical than other tumor cells." (PMID 28245823, 2017). "Tumour-selective pro-apoptotic activity of scFvFITC:sFasL was confirmed in a panel of 4 carcinoma cell lines pretargeted with either anti-EpCAM-FITC or anti-CD44-FITC." (PMID 29038485, 2017). "On the other hand, CD44 seems to exert a crucial role in tumor initiation and progression." (PMID 29348889, 2017). "In addition, we observed the correlated EMP3 and CD44 staining positivity in paraffin-embedded archival tumor specimens (n = 60, Spearman correlation r = 0.780, P < 0.0001." (PMID 27527869, 2017). "The comparative analysis of immunofluorescence results obtained from particulartumours (G113, G114 and G116) cultured as three experimental models (10%adh, 0% sph, 0% adh) revealed the presence of selected CSCsmarkers (SOX2, nestin and CD44) in G113 and G116 tumour-derived cells." (PMID 28522553, 2017). "OCSCC cell clones expressing stable levels of CD44 after transfection with CD44 expression vector increases proliferation and migration, inhibition of apoptosis, and cisplatin resistance resulting in a more aggressive tumor phenotype in vivo." (PMID 28626726, 2017). "However, poorly differentiated tumors show an inconsistent staining pattern with CD44, so it cannot be used in poorly differentiated neoplasms." (PMID 28099906, 2017). "In addition, cleavage of CD44 regulated by ADAM17 has been found to be necessary for tumor sphere formation in OTSCC cells." (PMID 28626726, 2017). "Based on the latest reviews on CSC markers in NPC cell lines, CD44, an extracellular receptor for hyaluronan, seems to be the most widely studied marker with roles ranging from tumour initiation, cell proliferation and differentiation to 5-fluorouracil treatment resistance." (PMID 28959019, 2017). "After demonstrating that high CD44/CD24 ratio correlated with proliferation and tumorogenesis while ALDH1+ correlated with tumor metastasis, we further verified the roles of high CD44/CD24 ratio and ALDH1+ by suppressing their expression in MDA-MB-231 cells using siRNA." (PMID 29062075, 2017). "Consistent with this, we demonstrate that supplementation with NC derived stromal cells promotes proliferation and tumor aggressiveness in vivo, increasing expression of mesenchymal genes such as CD44, S100A10, ENG, VIM and ACTA2 (SMA), being the last one a typical marker of CAFs." (PMID 29163787, 2017). "When up-regulated, CD44 increases tumor growth and anti-apoptotic property." (PMID 26840024, 2016). "Additionally, Yin and colleagues have shown that CD44+ (high claudin-4) cells have an enhanced ability to migrate compared to the CD44- (low claudin-4) population of the same tumor." (PMID 27724921, 2016). "Interaction between CD44 and its main ligand, hyaluronic acid (HA), may be important in tumor growth and treatment resistance via cell proliferation, differentiation, and migration." (PMID 27507056, 2016). "Not only will understanding the contribution of specific CD44 isoforms to tumor progression/suppression be beneficial in developing prognostic markers but it may also reveal specific variants that may have therapeutic potential." (PMID 27379207, 2016).
tumor (continued). "Analysis of potential biomarkers showed reduction of CD14+ monocytes in peripheral blood suggesting a PD effect of RG7356; one of the proposed modes of action is to trigger direct antitumor effects by activating CD68+ macrophages via Fc/FcgR interaction to phagocytose CD44-positive tumor cells." (PMID 27507056, 2016). "Therefore, it is conceivable that, in this kind of cases, the tumor cells rely on this new gained function for survival and inhibiting the CD44-HA interaction remains biologically less relevant." (PMID 27463372, 2016). "In control tumors there was a reduction in CD44 expression as tumor volume increased." (PMID 26880935, 2016). "The IHC positive staining of CD44, Shh, and Gli1 proteins was correlated with larger tumour size, worse gross type and histological type, and advanced TNM stage, which also predicted shorter overall survival (OS) and disease-free survival (DFS) after radical resection." (PMID 26839535, 2016). "Similarly, in basal-like tumor forming cell lines, the CD44+/24–/low cells were enriched in BRCA1-defective HCC1937 (52.7 ± 1.84 %) when compared to HCC1937/wt BRCA1 (30.6 ± 5.0 %) that possesses a wild type BRCA1." (PMID 27229859, 2016). "One of the compelling markers in tumor malignancies is cluster of differentiation 44 (CD44)." (PMID 27200096, 2016). "Conversely, FGFR2 overexpression increased CD44 and accelerated tumor growth in mice." (PMID 27107424, 2016). "In addition, GAPLINC can function as a tumor promoter by upregulating CD44, a cell surface glycoprotein known to facilitate tumor metastasis." (PMID 27686732, 2016). "Taken together, our present findings implicate that the blockade of MMP2 and CD44 expressions as well as MMP-2 activity may contribute to the inhibitory effect of grifolin on tumor cell migration and adhesion." (PMID 27626695, 2016). "With respect to CD44, the interaction between CD44 and its ligand, hyaluronic acid, may inhibit angiogenesis and tumor progression." (PMID 27285762, 2016). "CD44 is a cell surface HA-binding glycoprotein that is overexpressed to some extent by almost all tumors of epithelial origin and plays an important role in tumor initiation and metastasis." (PMID 27200096, 2016). "Although mounting evidence suggests the involvement CD44 in tumor progression, the roles of CD44 as well as its utility as a biomarker for primary tumors remains controversial due to its dual functions as a tumor promoter or suppressor and altered expression in CD44v." (PMID 27220365, 2016). "Elevated expression of β1, CD44 or both combined by the cancer cells may promote tumor cell adhesion and lead to increased tumor aggressiveness." (PMID 27835603, 2016). "Moreover, this is the first study to demonstrate that patients with CD44-negative tumours have better overall survival and lower recurrence rate than patients with CD44-positive tumours after radical surgery." (PMID 26839535, 2016). "The results showed that CD49f+/CD44+/CD24− cells were 13.6% of the whole tumor cell population." (PMID 27374087, 2016). "This phototheranostic strategy provides an opportunity to selectively eliminate aggressive CD44 populations in primary and metastatic TNBC, and for those TNBCs that uniformly express CD44, the opportunity to eliminate the entire population of cancer cells in the tumor." (PMID 27302409, 2016). "The MET/CD44 axis seems to be an important component of the CSC response in this HNSCC tumor model." (PMID 26880935, 2016). "Although IHC staining showed that the number of CD44+ staining cells was not significantly different between the groups, the intensity of CD44+ staining were markedly weaker in tumor tissues from YM155-treated mice compared to those in tumor tissues from vehicle-treated mice." (PMID 26771139, 2016).